BRD4 (bromodomain containing 4)
Diseases named in the same sentence as BRD4 in open-access papers (continued):
Sharing a sentence is not in itself a finding about the gene and the disease.
tumor (continued). "This technology has been also applied to inhibit BRD4 in Burkitt’s lymphoma cell lines, leading to MYC depletion accompanied by tumor regression in a xenograft model." (PMID 36969025, 2023). "In several NCs, including TC-797 (BRD4-NUT+, thymus), PER-403 (BRD4-NUT+, lung), 1015 (BRD4-NUT+, lung), and tumor tissue from which 1015 was derived, massive hyperacetylated domains were observed that encompass many regulatory genes including ALX114." (PMID 36690674, 2023). "For example, the BRD4 inhibitor JQ1 can induce neuron-like differentiation and delay tumor growth in a mouse model of DIPG, and the CDK7 inhibitor THZ1 can disrupt transcription and inhibit DIPG growth." (PMID 36720920, 2023). "ARV@PDSA‐mediated BRD4 degradation and c‐Myc downregulation of B16F10 tumor cells were also demonstrated by western blot and IHC staining assays." (PMID 37066758, 2023). "BRD4 inhibition by JQ1 was a typical example of interfering LLPS of MED1/BRD4 at super enhancer that disrupted down-stream signaling and inhibited tumor cell proliferation." (PMID 37917664, 2023). "JQ1 is a potent inhibitor of bromodomain-containing protein 4 (BRD4), which abolishes IFN-γ-induced PD-L1 expression on the surface of tumor cells, thus overcoming the acquired immune suppression." (PMID 37328484, 2023). "Compound 65 was shown to induce autophagy in tumor cells via the BRD4-AMPK-mTOR-ULK pathway and exhibits a striking anti-tumor activity in breast cancer xenograft models and zebrafish in vivo." (PMID 37142850, 2023). "Bromodomain-containing protein 4 (BRD4), an epigenetic reader of histone acetylation, is highly expressed in different types of tumor cells, and it can protect these tumor cells against targeted therapy and immunogenic cell death." (PMID 36600243, 2023). "With the ability to efficiently displace chromatin-bound BRD4, compound 68 is considered to have the potential to be an alternative to pan-BET inhibitors in tumor therapy." (PMID 37142850, 2023). "Treatment with BRD4 inhibitors results in KDM6A mutant pancreatic cancer cell differentiation and tumor growth inhibition in a mouse model." (PMID 38135679, 2023). "Targeting essential components of super-enhancers, such as BRD4 and CDK7, has been shown to result in potent anti-tumor effects in preclinical and clinical studies." (PMID 37460542, 2023). "Inhibition of BRD4 also blocks proliferation of TAMs, upregulates expression of MHC molecules, and induces immunogenic cell death of tumor cells." (PMID 37685868, 2023). "Studies have confirmed that PROTACs can effectively induce the degradation of Brd4, which is more effective than JQ1 and other traditional Brd4 inhibitors in inhibiting tumor cell growth and promoting cell apoptosis." (PMID 36539410, 2022). "SPOP exerts its tumor suppressor roles mainly by promoting the degradation of its oncogenic substrates, such as AR, ERG, BRD4, and Nanog6,8,9." (PMID 35233061, 2022). "Hence, Brd4 inhibition-induced pyroptosis may enhance anti-tumor immunity." (PMID 36539410, 2022). "When we employed BRD4 knockdown in one of the BRD4-high cell lines SGC7901, a clear suppression of tumor growth was observed in BRD4-compromised cells, which implied a direct antitumor function of BRD4 blockage." (PMID 36352160, 2022). "Analysis of their expression levels in tumor patients and normal subjects identified five core prognostic markers, which were EIF4EBP1, BCL2A1, NDRG1, ERRFI1 and BRD4." (PMID 36524001, 2022). "The novel BTK/PI3K/BRD4 inhibitor, SRX3305, demonstrates marked anti-tumor properties in preclinical models of CLL." (PMID 35743155, 2022).
tumor (continued). "One classical example is the targeted suppression of the bromodomain and extra-terminal domain (BET) including bromodomain-containing protein 4 (BRD4), which displays superiority of inhibiting tumor growth." (PMID 36157053, 2022). "Recently, researchers combined the SMO inhibitor MRT-92 and a Proteolysis Targeted Chimeras (PROTACs)-derived BRD4 degrader (MZ1), to treat the tumor and found that it remarkably suppressed tumor growth." (PMID 35267473, 2022). "Of note, the half inhibition concentrations (IC50) of the PROTACs were tens of times lower than that of the BRD4 inhibitor JQ1, suggesting that the BRD4 degraders more significantly impaired the proliferation of the tumour cells than the BRD4 inhibitor." (PMID 35882867, 2022). "BRD4 is a member of the BET family proteins and mediates super-enhancer–driven addiction of tumor cells to oncogenic drivers in a context-dependent fashion." (PMID 35881485, 2022). "Environmentally activatable ENCTAC formation and BRD4 protein degradation were confirmed upon incubation of NTR-pomalidomide and JQ1-CBT substrates in hypoxic cell and animal models of angiogenesis with tumor." (PMID 36516252, 2022). "In this work we rationally engineer a polymeric PROTAC (POLY-PROTAC) nanoplatform for tumour-targeted degradation of the bromodomain and extraterminal (BET) protein BRD4." (PMID 35882867, 2022). "Bromodomain-containing protein 4 (BRD4), a BET family, is especially known to influence the tumor immune surveillance." (PMID 36614001, 2022). "BRD4 inhibitors, JQ1 and ARV771, have shown a wide range of anti‐tumour activity in different types of cancer with manageable toxicity." (PMID 35083874, 2022). "ARV-825, consisting of a BRD4 inhibitor conjugated with a cereblon ligand using proteolysis-targeting chimera (PROTAC) technology, was proven to decrease the tumor growth effectively and continuously." (PMID 34733788, 2021). "While the role of SPOP protein differs depending on the tumor type, in prostate cancer, SPOP seems to function as a tumor suppressor and its targets for degradation, among others, include AR, ERG, steroid receptor coactivator 3 (SRC3), BRD4, MYC, and TRIM24." (PMID 33572160, 2021). "The transcriptional element, for example, bromodomain-containing protein 4 (BRD4) and cyclin-dependent kinase 7 (CDK7), has been reportedly the treatment target due to tumor-specific SEs." (PMID 34722892, 2021). "Pharmacological inhibition of BRD4 decreased NRP1 expression and ablated FGF-mediated tumor cell growth." (PMID 33128042, 2021). "Overall, our findings reinforce previous studies describing that the inhibition of both BRD4 and the ERBB2 downstream PI3K pathway produces antitumoral activity in different tumor cell lines." (PMID 33741018, 2021). "Co-targeting BRD4 and RAC1 precipitated very significant anti-growth effects in BRCA cells in vitro and inhibited tumor growth in vivo." (PMID 34803511, 2021). "Mechanistically, through comprehensive biochemical screening and tumor samples profiling, we identified UCHL3 as a crucial deubiquitinase that binds explicitly to JAK2-phosphorylated BRD4 to maintain its stabilization." (PMID 34290255, 2021). "The tumor-promoting activity of SNHG18 is largely attributed to antagonization of miR-211-5p and upregulation of BRD4." (PMID 33500406, 2021). "The genetic depletion of BRD4 resulted in a stark decrease in tumour growth and improved survival when xenografted into mice, demonstrating the dependence of DIPG tumours on BRD4." (PMID 34944870, 2021). "Myc can be transcriptionally regulated by BET bromodomain protein 4 (BRD4), and BET bromodomain inhibitor JQ1 selectively downregulates MYC and MYC-dependent target genes and showed anti-tumor effects of hematological malignancies and NSCLC." (PMID 33572152, 2021). "Western blots were performed to evaluate the expression of BRD4 and ERBB2 in tumor lysates at the end of treatment." (PMID 33741018, 2021).
tumor (continued). "Collectively, these data indicated that lapatinib and JQ1 cooperatively disrupt BRD4 and MED1 chromatin binding at a majority of genomic loci, consistent with their capacity to elicit potent effects on adaptive responses and suppress tumor cell growth." (PMID 33980863, 2021). "Collectively, our results demonstrate that inhibition of BET or CARM1 significantly blocks tumor growth and metastasis in PDX models, possibly through inhibiting expression of SE-regulated oncogenes because this mechanism is shared between BRD4 and me-BAF155." (PMID 34865122, 2021). "The combined inhibition of epi-factors, e.g., P300/CBP (by GNE-781) and BRD4 (by OTX015), have been also applied for decommissioning oncogenic enhancers (e.g., MYC enhancers), and can increase the anti-tumour efficacy." (PMID 34298745, 2021). "Inhibition of BRD4 by JQ1, dBET, or iBET significantly blocked proliferation and in vivo tumor growth of different EwS lines and strikingly resulted in a strong down-regulation of the EWS-FLI1 mediated transcription program (Becker-Dettling, data not shown)." (PMID 32012890, 2020). "Bromodomain-containing protein 4 (BRD4) is an epigenetic reader that recognizes histone proteins and acts as a transcriptional regulator to trigger tumor growth and the inflammatory response." (PMID 32765266, 2020). "Collectively, these data reveal a strong similarity between the concurrent inhibition of the integrin-FAK and BRD4-c-Myc axes and current therapies in NSCLC in terms of their anti-tumor cell growth effects." (PMID 32793596, 2020). "TPL-mediated disruption of cell-specific SEs to downregulate gene expression (MYC, BRD4, RNA Pol II, COL1A2, etc.), as elucidated here, implies its therapeutic relevance in targeting both stromal and tumor compartments of PDAC." (PMID 33168807, 2020). "Immunohistochemical analysis of the tumor tissues revealed a statistically significant (P-value < 0.05) reduction in staining for HSP70, MYC, BRD4, and αSMA in Minnelide-treated mice." (PMID 33168807, 2020). "BRD4 protein degradation as well as c-Myc, Bcl-xL and cyclin D1 downregulation were detected in ARV-825-treated TPC-1 tumor tissues." (PMID 32163373, 2020). "Western blotting results indicated that the protein level of BRD4, c-Myc, CyclinD1, CDK4, MMP-2, MMP-9, Vimentin and N-cadherin were all decreased while E-cadherin was increased in the tumor with circCELSR1 knockdown." (PMID 32640974, 2020). "Our screening analysis revealed that JQ1 and IBET-762, inhibitors of epigenetic reader BRD4, and LBH589, a pan inhibitor of histone deacetylases (HDACs), exhibited synergy with VS-6063 in mitigating tumor cell viability." (PMID 32793596, 2020). "Although hypoxia increased the recruitment of BRD4 to CA9 and VEGF-A in tumor cells, the down-regulated CA9 and VEGF-A in tumor cells treated with JQ1 indicated that JQ1 affected the hypoxia response in which BRD4 participated." (PMID 33109235, 2020). "VS-5584 treatment of 786-O tumor xenografts and RCC cells resulted in feedback upregulation of bromodomain-containing protein 4 (BRD4)." (PMID 33051401, 2020). "TPL treatment (20 nM and 100 nM for 24 h) reduced the protein expression levels of BRD4, MYC, and RNA Pol II in the tumor cell lines." (PMID 33168807, 2020). "Both SF1126 and SF2523, orthogonally hit PI3K and BRD4 signaling, which blocks MYCN expression, activation and promotes MYCN degradation, ultimately leading to reduced tumor growth, angiogenesis and tumor metastasis." (PMID 32722460, 2020). "Subcutaneous tumor transplantation test showed that, compared with PANC-1/BRD4-nc, PANC-1/BRD4-sh1 and PANC-1/BRD4-sh2 groups had slower growth rate and tumor weight." (PMID 32099528, 2020). "In consistence with in vitro results, ARV-825 treatment downregulated BRD4 and MYCN protein expression in xenograft tumor." (PMID 33324552, 2020).
tumor (continued). "I have also highlighted on the dual PI3K/BRD4 inhibitory chemotypes SF1126 and SF2523 which can concomitantly inhibit several tumor promoting signaling pathways and can activate anti-tumor immune response by blocking myeloid cell mediated immunosuppression." (PMID 32722460, 2020). "Confocal fluorescence imaging was then used to examine the interaction between ISX, BRD4, and PCAF in immunostained samples of tumor masses and adjacent healthy lung tissues from patients with NSCLC." (PMID 31908141, 2020). "Inhibition of BRD4, by either genetic knockdown or JQ1, suppressed cell proliferation in RCC cells and impaired tumor growth in human RCC xenografts in mouse model." (PMID 32303673, 2020). "Analyzing tumor tissue lysates by western blots demonstrated that BRD4-regulate proteins (Bcl-2, Myc, cyclin D1) were significantly downregulated in I-BET726-treated A431 tumor tissues." (PMID 32371868, 2020). "MYC transcription is under the regulation of Bromodomain-containing 4 (BRD4) and a BRD4 inhibitor, JQ1, was found to possess anti-tumor effects." (PMID 32748879, 2020). "Immunohistochemical staining of macrophages (CD68+ cells), p-BRD4 and CSF1 showed that macrophages were present in nearly all these implantation tumors, and p-BRD4 and CSF1 were expressed mostly in tumor cells." (PMID 32286255, 2020). "In a previous study, we have found that bromodomain containing 4 (BRD4), the primary BET family member is overexpressed in most HCC tumor tissues." (PMID 31993368, 2019). "Lastly, among different stages of LUAD, later Tumor, Node, Metastasis (TNM) stages exhibited higher BRD4 expression (BRD4 expression was higher in TNM stages III and IV than in TNM stages I and II." (PMID 30988278, 2019). "To further investigate the anti-tumor effect of JQ1 in a variety of HCC cells, we assessed the expression levels of BRD4 and MYC in ten HCC cell lines." (PMID 30770740, 2019). "BET inhibitors competitively interact with the bromodomain of BRD4 to displace the oncogenic protein fused with BRD and inhibit tumor cell growth." (PMID 31718704, 2019). "Based on these findings, and on the detrimental effects of BRD4 depletion on AML proliferation, many inhibitors targeting BET proteins have been designed and tested against several tumor types, including leukemia." (PMID 31681756, 2019). "We showed that JQ1 decreased the binding of BRD4 to the MYC promoter to suppress MYC transcription, leading to decreased tumor cell proliferation." (PMID 30459933, 2018). "Recently, inhibitors of BRD4, a BET (bromodomain and extra-terminal domain) family member, have shown significant effects in hindering tumor growth by suppressing the expression of oncogenes." (PMID 30518851, 2018). "miR-3140 downregulated the expression of BRD4-NUT fusion protein and MYC, and suppressed tumor cell growth in Ty-82 JQ1-R cells as well as Ty-82 cells." (PMID 29540837, 2018). "Interrogation of BRD4-amplified HGSOC TCGA data revealed an enriched ERBB2 signature, consistent with activated NRG1 signaling in this tumor subset." (PMID 30036377, 2018). "PVAX is developed by encapsulating JQ1 (a BRD4 inhibitor) and indocyanine green (ICG) co-loaded tumor cells with a hydrogel matrix." (PMID 29670088, 2018). "In both BRD4 amplified models, over the 25-day course of drug administration, at 5 and 10 mg/kg QD, AZD5153 led to tumor stasis, with 100% tumor growth inhibition (TGI) in OV0857F and 98% TGI in HOXF062 respectively." (PMID 30036377, 2018). "BRD4 recruitment at the E3 ubiquitin-ligases MuRF1 and MAFbx/Arogin1 genes was reduced in skeletal muscles of (+)-JQ1-treated C26-tumor-bearing mice." (PMID 29167426, 2017). "Interestingly, de Raedt and colleagues provided evidence that BRD4 inhibition by JQ1 exerted only a modest, cytostatic effect on human MPNST cell lines and that only the combination of JQ1 with PD-901, a MEK-inhibitor, caused a tumor growth inhibition and regression." (PMID 28813519, 2017).
tumor (continued). "Inhibition of Brd4, which was found highly upregulated in MPNST, induced increased expression of the pro-apoptotic molecule Bim inducing apoptosis in MPNST cells and tumor shrinkage." (PMID 28813519, 2017). "With respect to BRD4, it has been shown that inhibition of this protein profoundly suppresses MPNST tumorigenesis and tumor cell growth in a murine MPNST model." (PMID 28813519, 2017). "Inhibition of BRD4 in thyroid cancer cells by JQ1 has been demonstrated to decrease cell viability in vitro and suppress tumor growth in vivo." (PMID 28545522, 2017). "In the present study, we found that BRD4 expression was increased in HCC cell lines and tumor tissue and correlated with HCC disease progression." (PMID 26575167, 2016). "Bromodomain containing protein 4 (BRD4), a member of the bromodomain and extra terminal domain (BET) protein family, has been shown to play important roles in tumor progression." (PMID 26840017, 2016). "These inhibitors have been shown to inhibit BRD4 chromatin interactions, thereby blocking MYC-mediated tumor growth and survival." (PMID 27631103, 2016). "In addition, although JQ1 stimulated anti-HCC activity in vitro, treatment with JQ1 at 50 mg/kg twice daily in vivo had only a modest effect on tumor growth, suggesting that BRD4 inhibitors with increased bioavailability or potency may be required for improved therapeutic responses." (PMID 26575167, 2016). "We further show that this upregulation of MYC is mediated by BRD4 regulation of the MYC gene and that combining a BRD4 inhibitor with everolimus leads to enhanced tumor growth inhibition in vitro and in vivo." (PMID 25537515, 2015). "Molecular analysis of the tumor tissue identified a novel in-frame BRD4-NUT transcript, with BRD4 exon 15 fused to the last 124 nucleotides of NUT exon 2 (BRD4-NUT ex15:ex2Δnt1–585)." (PMID 26551281, 2015). "We have previously shown that a relationship between BRD4-LF, RRP1B and SIPA1 is critical for tumor progression and extracellular matrix regulation." (PMID 24260471, 2013). "Although investigation into the mechanisms by which BRD4 influences cyclin D1 expression was beyond the scope of this paper, further investigation of this interaction could be of clinical relevance, considering the importence of the cyclin D family in tumor maintenance." (PMID 24231268, 2013). "In our previous work, we demonstrated that liposomal encapsulation could significantly improve the solubility and tumor-targeting efficiency of ARV825, a BRD4-targeting PROTAC." (PMID 41567737, 2026). "Furthermore, in CT26 tumor-bearing mice, Alb-TAC#2 achieved extensive apoptosis through robust BRD4 degradation, leading to marked downregulation of c-Myc, Bcl-2, and PD-L1." (PMID 42094600, 2026). "It interacts with BRD4, and targeting both BRD4 and AURKA reduces tumor growth." (PMID 40949882, 2025). "After treatment, there was a nonsignificant reduction of tumor volumes in both BRD4 WT and BRD4 cKO mice." (PMID 40762981, 2025). "Moreover, BRD4 is highly expressed in HNSCC, and BET inhibition has shown to increase anti-tumor immunity in HNSCC by enhancing major histocompatibility complex class I expression." (PMID 40858106, 2025). "BRD4 inhibition with JQ1 disrupted immunosuppressive gene activation, and its combination with EGFR CAR-T therapy reduced immunosuppression, effectively curbing tumor growth and metastasis in GBM xenografts." (PMID 40565099, 2025). "Inhibiting BRD4 with BET inhibitors repressed cMYC expression, leading to tumor suppression." (PMID 41249136, 2025). "Consistent with our observations, inhibition of BRD4 by JQ-1 suppressed erastin-induced ferroptosis in CALU1 and HT1080 cells and abrogated the anti-tumor effects conferred by erastin in a lung metastasis model by protecting mitochondrial function and reducing lipid ROS formation." (PMID 40695797, 2025).